NF1 (neurofibromin 1)
Diseases named in the same sentence as NF1 in open-access papers (continued):
Sharing a sentence is not in itself a finding about the gene and the disease.
neurofibroma (continued). "NF1 is caused by inactivating mutations in the NF1 gene and loss of heterozygosity of this gene has been reported in neurofibromas, malignant peripheral nerve sheath tumors, gliomas and pheochromocytomas in patients with NF1." (PMID 24137429, 2013). "In NF1 patients, Schwann cells are believed to be the primary pathogenic cell source in neurofibromas because they show biallelic NF1 gene mutations." (PMID 23319880, 2012). "The tumor microenvironment is also known to impact upon the development of NF1-associated tumors, with mast cells a likely contributor to neurofibroma development." (PMID 23244685, 2012). "As with benign neurofibromas, malignant NF1-associated tumors are known to be heterogeneous in nature, invariably containing diverse subpopulations of tumor cells, including benign and malignant cells, fibroblasts, and infiltrating inflammatory cells." (PMID 23244685, 2012). "It has also been suggested that neurofibromas are caused by somatic inactivation of the wild-type NF1 allele, leading to complete functional abrogation of the gene." (PMID 22550514, 2012). "The development of tumors, café au lait spots, and neurofibromas is caused by spontaneous somatic mutations in the one remaining intact NF1 gene leaving these cells unable to express neurofibromin." (PMID 23304574, 2012). "Pten immunohistochemistry shows a significantly (p = 0.045, Pearson correlation) reduced Pten expression in MPNST (n = 16, 3 sporadic and 13 NF1-associated MPNST) as compared to neurofibromas (n = 16)." (PMID 23139750, 2012). "Loss of heterozygosity (LOH), for example, represents a common form of loss of function of the wild-type NF1 allele in somatic cells such as Schwann cells which form neurofibromas, owing to the presence of an inherited NF1 gene lesion on the other allele." (PMID 23244685, 2012). "Mutation of the NF-1 gene and dysfunction of neurofibromin lead to uncontrolled cell proliferation and development of some tumors, including neurofibroma, glomus tumor, carcinoid tumor, and gastrointestinal tumor." (PMID 22824559, 2012). "We have previously demonstrated the synergistic role of Pten inactivation to plexiform neurofibroma tumorigenesis and progression to high-grade PNSTs in the context of neurofibromatosis 1 (Nf1) loss in Schwann cells and/or their precursor cells." (PMID 23319880, 2012). "In one tumor we identified the first example of a neurofibroma-associated second-hit type-2 NF1 deletion." (PMID 21031597, 2011). "We believe that having a clear picture of the frequency of LOH in dNFs and understanding the importance of the different mechanisms underlying NF1-LOH is necessary for any further attempt to identify genes influencing neurofibroma development." (PMID 21031597, 2011). "Most homologous recombination crossovers underlying LOH in neurofibromas were found to be located between the centromere and the NF1 gene." (PMID 21031597, 2011). "The increased risk in NF-1 patients with subcutaneous neurofibromas (high risk phenotype) can be ascribed in part to the associations between SC-NFs and internal neurofibromas (prone to transformation to MPNSTs) and the presence of a neuropathy with SCVs." (PMID 21752287, 2011). "Most sporadic (64%) and most NF1-associated (53%) neurofibromas were located in the supraclavicular brachial plexus and the remainder were in an infraclavicular location." (PMID 21838856, 2011). "The at-risk phenotype of NF-1 patients (i.e. NF-1 patients with SC-NFs) is ascribable to associations linking SC-NFs to internal neurofibromas at risk for malignant transformation and to axonal neuropathies with slowed conduction velocities." (PMID 21752287, 2011). "Genes controlling the integrity of the DNA are likely to influence the number of neurofibromas developed because dNFs are caused by somatic mutational inactivation of the NF1 gene, frequently evidenced by loss of heterozygosity (LOH)." (PMID 21031597, 2011).
neurofibroma (continued). "NF1-related neurofibromas are associated with somatic mutations at the NF1 gene, a tumor suppressor gene located in the pericentromeric region of chromosome 17." (PMID 20858283, 2010). "Recent studies have reported that mutations at the NF1 gene in Schwann cells are responsible for tumorigenesis of NF1-associated neurofibromas." (PMID 20858283, 2010). "In the gastrointestinal (GI) tract, NF-1 is associated with neurofibroma, leiomyoma, and adenocarcinoma in the stomach, small and large bowel, vasculopathy, bleeding, pseudoobstruction, and protein-losing enteropathy." (PMID 19568560, 2009). "NF1-associated neurofibroma, malignant schwannomas, medulloblastoma, astrocytoma, and pheochromocytoma derive from cells of neural crest origin." (PMID 16961930, 2006). "Among these cutaneous findings, neurofibromas are the hallmark lesions of NF1." (PMID 41598414, 2026). "Biopsy demonstrated benign neurofibroma, and genetic testing confirmed a mutation in the NF1 gene." (PMID 41487410, 2025). "While NF1 patients have systemic loss of one NF1 allele due to a germline mutation, it is the acquisition of a second, somatic mutation in the remaining wild-type NF1 gene, specifically in Schwann cells, that gives rise to neurofibromas." (PMID 41294711, 2025). "In addition to neurofibromas, individuals with NF1 are predisposed to other tumor types, particularly astrocytomas and gliomas." (PMID 41294711, 2025). "NF1 microdeletion syndrome, which involves the deletion of large segments of the NF1 gene and its flanking region, is associated with more severe phenotypes, as evidenced by our findings in a large number of neurofibromas." (PMID 39857730, 2025). "An ongoing clinical trial NCT03363217/TRAM-01 aims to study trametinib as a monotherapy in a basket trial involving four groups of progressive tumors (KIAA1540-BRAF fusion, NF1-associated plexiform neurofibromas, NF1-associated other gliomas, and other MAPK-ERK pathway–activated gliomas)." (PMID 40094009, 2025). "Interim results of a phase 2 study of single-agent trametinib demonstrated an overall response rate of around 47% (complete, partial, or minor response) in pLGG and a 60% response rate using volumetric assessments in patients with NF1-associated plexiform neurofibroma." (PMID 40007996, 2025). "We were unable to identify a microdeletion of the NF1 gene as a determinant in the occurrence of plexiform neurofibroma morbidity, while current literature suggests an association between NF1 microdeletions and an increased incidence of high tumor burden in PNs." (PMID 39796750, 2025). "Loss of neurofibromin function through germline NF1 mutations predisposes to a spectrum of tumors and hamartomas, most notably plexiform neurofibromas and optic pathway gliomas (OPGs), with the latter occurring in roughly 15-20% of children with NF1 and causing visual loss in a subset." (PMID 41341331, 2025). "However, other studies have observed an increase in tumor volume in a GEMM model of plexiform neurofibroma harboring germline NF1-LOF mutations following tovorafenib treatment." (PMID 40111124, 2025). "Complete Nf1 loss of function in SCs correlates with neurofibroma formation." (PMID 38258905, 2024). "Screening somatic mutations in the neurofibroma tissues may also identify mutations causing NF1 in these patients." (PMID 38596211, 2024). "There are mutations in both Nf1 alleles in neurofibromas and neurofibroma SCs." (PMID 38258905, 2024). "To test this hypothesis, we analyzed a panel of patient-derived neurofibroma or MPNST cells with inactivating NF1, CDKN2A/B, or PRC2 mutations." (PMID 38216572, 2024). "Additionally, schwannomas and neurofibromas are tightly linked with genetic conditions such as neurofibromatosis type 1 (NF1) and NF2, with schwannomatosis emerging as a separate syndrome associated with SMARCB1 mutations." (PMID 39001422, 2024). "Neurofibromas, as a hallmark of NF1, are extremely rare in patients with other RASopathies." (PMID 39006611, 2024).
neurofibroma (continued). "Neurofibromas result from loss of NF1 heterozygosity following second-hit mutations." (PMID 39217323, 2024). "Magnetic resonance imaging (MRI) at 16 years of age revealed a right pontine hamartomatous lesion associated with NF1, a 35 mm neurofibroma in the medial mandibular ramus, and suspected neurofibromas in the right buccal and left mandibular subcutaneous regions." (PMID 38755192, 2024). "This is of special value for NF1 cohorts who might have a high inner tumor load or complex and invasive plexiform neurofibroma lesions, and are therefore at a high risk of malignant transformation to MPNSTs at about 10% over their lifetime." (PMID 39594712, 2024). "Notably, the recently published ReNeu trial found that children with NF-1 associated inoperable symptomatic plexiform neurofibromas treated with intermittent dosing of Mirdametinib (3 weeks on/1 week off) met the primary efficacy endpoint, with ORR of 52%." (PMID 39759151, 2024). "Of note, the administration of selumetinib, a MAP kinase (MEK) 1/2 inhibitor which was revealed to be helpful to treat NF1-associated tumors such as plexiform neurofibromas and optic way gliomas, has been recently associated with revascularization failure in NF1-related MMS." (PMID 38316674, 2024). "Ranked from most AgNP-sensitive to least AgNP-sensitive are NF1-associated MPNSTs (NF1−/−); NF1-associated plexiform neurofibroma (NF1−/−); NF1-associated Schwann cells (NF1+/−); and Schwann cells (NF1+/+), which also corresponds to the increasing gene dose of functional neurofibromin." (PMID 38543265, 2024). "Loss of NF1 heterozygosity in Schwann cells (SCs), the cells of origin for these nerve sheath-derived tumors, leads to the formation of plexiform neurofibromas (PNF)—benign yet complex neoplasms involving multiple nerve fascicles and comprised of a myriad of infiltrating stromal and immune cells." (PMID 38473354, 2024). "When we dichotomized benign neurofibromas based on NF1 syndrome status, only 14% (2 of 14) of sporadic neurofibromas harbored somatic NF1 gene mutations, which suggests sporadic neurofibromas may have different mechanism of RAS pathway activation." (PMID 37164978, 2023). "Our study did suggest that the NF1-associated were most distinct from neurofibromas at both the genomic and transcriptomic levels, and this could result in distinct molecular prognostic factors between NF1-associated and sporadic MPNSTs." (PMID 37837931, 2023). "Various types of neurofibromas may develop based on the stage in which NF-1 mutation in Schwann cells occurs." (PMID 37274990, 2023). "Apart from the neurological system, NF1 has been linked to an elevated relative risk of other malignancies, such as neurofibromas, which represent benign nerve sheath tumors originating from non-myelinating Schwann cells, and they are considered a characteristic feature of NF1." (PMID 37181996, 2023). "This suggests that gentamicin, for example, could reach therapeutic levels at a lower dose for NF1-associated optic pathway glioma compared with cutaneous manifestations of NF1, like neurofibromas." (PMID 37520682, 2023). "Multiplex ligation-dependent probe amplification (MLPA) analysis was performed to check whether the loss of heterozygosity due to deletion of one NF1 allele can be detected in the plexiform neurofibroma." (PMID 37569527, 2023). "Neurofibromatosis type 1 (NF1) is a common autosomal dominant genetic disorder characterized by mutations in NF1, associated with almost universal development of cutaneous neurofibromas, as well as plexiform neurofibromas, optic pathway glioma (OPG), and malignant peripheral nerve sheath tumors." (PMID 37124503, 2023). "The current TRAM-01 trial is a phase II basket trial including four groups of progressive tumors (NF1-associated gliomas, NF1-associated plexiform neurofibromas, KIAA1540-BRAF fusion gliomas, and other MAPK-ERK pathway–activated gliomas), treated with trametinib monotherapy (NCT03363217)." (PMID 37124503, 2023).
neurofibroma (continued). "Several studies over the last decade have indicated that NF1-associated MPNSTs typically begin as plexiform neurofibroma (PN) and atypical neurofibromatous neoplasm of unknown biological potential (ANNUBP)." (PMID 36831419, 2023). "These tumors are composed of neoplastic NF1-deficient Schwann lineage cells and are classified as either cutaneous (discrete dermal) or plexiform (diffuse) neurofibromas." (PMID 35188187, 2022). "Conversely, malignant peripheral nerve sheath tumors are soft tissue sarcomas that may arise from a peripheral nerve or a pre-existing neurofibroma, and in about 50% of cases, these tumors are associated with NF1." (PMID 35741273, 2022). "Despite the different types, both sporadic and NF1-associated neurofibromas may contain focal or diffuse nuclear atypia in the absence of increased mitotic activity (≥1 mitosis/50 HPF) and/or hypercellularity." (PMID 35741273, 2022). "In addition, in individuals with missense mutations affecting NF1 codons 844–848 or pArg1276, multiple spinal neurofibromas were more common." (PMID 36612057, 2022). "Neurofibroma/perineurium combinations are unusual and are generally linked with NF1." (PMID 36721607, 2022). "Since loss of functional NF1 in normal Schwann cells is an initiating event in the formation of plexiform neurofibroma, and ultimately, in malignant transformation, we challenged the neurofibromin-reduced and control cells with standard of care MEK inhibitor selumetinib." (PMID 35887576, 2022). "Patient Three who presented with café au lait macules and young-onset plexiform neurofibroma at age 32 was heterozygous for a pathogenic NF1 frameshift variant (c.2033dup) that has previously been reported in multiple individuals with NF-1 around the world, including from Asia." (PMID 35698239, 2022). "This particular subset of patients with NF-1 experiences limited improvement after surgical excision of plexiform neurofibromas along with a high risk of perioperative complications and a high recurrence rate, which is frustrating for both the patients and clinicians." (PMID 35455674, 2022). "Therefore, one potential model for MPNST development proposes that bi-allelic NF1 loss occurs in nerve-sheath precursor cells, resulting in benign neurofibroma formation." (PMID 35053663, 2022). "Recent results from trials initiated by the Neurofibromatosis Clinical Trials Consortium (NFCTC) have been extremely promising, demonstrating that Selumetinib (KOSELUGO, AstraZeneca, Cambridge, UK), a MEK inhibitor, can significantly reduce the size of NF1-associated plexiform neurofibromas." (PMID 34917731, 2022). "The patient P36 had two plexiform neurofibromas and many other types of tumors in one area of the body, but there was no detectable NF1 pathogenic variation in DNA isolated from peripheral blood sample, which was suggestive for segmental NF1." (PMID 34325699, 2021). "NF1 loss of heterozygosity (LOH) in the Schwann cell lineage leads to neurofibroma development, NF1−/− melanocytes lead to café-au-lait macules and Lisch nodules, NF1−/− osteoblasts lead to pseudoarthrosis of the tibia, and NF1−/− in glial cells leads to astrocytomas." (PMID 34945792, 2021). "Since there are no hotspot mutations in NF1, we chose NF1R1947X, a nonsense mutation that has been found in a relatively large subset of NF1 patients and is associated with a wide spectrum of disease including neurofibromas, optic gliomas, and skeletal abnormalities." (PMID 33669386, 2021). "However, testing of cutaneous neurofibromas from the proband showed a frameshift variant, c.495_498del:p.Thr165fs, in exon 5 of NF1." (PMID 33767727, 2021). "Regarding the mutations we found in our patients collective, targeted therapy has been used with success in adenocarcinoma of the lung with EGFR mutations, PIK3 inhibitors in stage four melanoma or MEK inhibitors in inoperable plexiform neurofibromas with NF1 mutations." (PMID 34065301, 2021).
neurofibroma (continued). "Our study on a MNF1 cohort and a review of literature showed that NF1-associated complications such as plexiform neurofibromas and cognitive impairment are present relatively often in patients with MNF1, and that debut of complications can occur rather late in life." (PMID 33853649, 2021). "The genetically engineered mouse model will be utilised to test whether blockade of STAT3 in earlier stages of NF1-associated nerve sheath tumour progression in plexiform neurofibroma and/or MPNST may have utility in MPNST chemoprevention." (PMID 33658640, 2021). "The development of neurofibromas result as a loss of a second allele, although this cannot be established in all neurofibromas, possibly due to the complex and large NF1 gene or to the existence of other, so far unknown genes involved in a second hit." (PMID 32494969, 2020). "Importantly, children and adolescents with NF1 microdeletions exhibit more often externally visible and internal plexiform neurofibromas than age-matched patients with intragenic NF1 mutations." (PMID 32533297, 2020). "In NF1, loss of the NF1 tumor suppressor gene that encodes the Ras GTPase-activating protein neurofibromin leads to the development of benign neurofibromas that are located on the skin (cutaneous neurofibromas) or can be deep-seated in large peripheral nerves (plexiform neurofibromas)." (PMID 32315290, 2020). "In addition, such EMT-related transcription factors are up-regulated in cultured NF1 Schwann cells and NF1-associated neurofibroma specimens." (PMID 32244473, 2020). "Up to 90% of NF1 patients develop NF1-associated tumours called neurofibromas." (PMID 32102484, 2020). "The development of plexiform neurofibromas (PN) follows Knudsen’s two-hit hypothesis with loss of heterozygosity of the NF1 tumor suppressor gene, the likely initiating rate-limiting event for tumorigenesis." (PMID 32252413, 2020). "However, the various neurofibromas occur in Nf1 DI mouse models in relatively few sites where mutated SC and BCCs are located." (PMID 31107888, 2019). "Therefore, glial cell Runx1/3 regulates Nf1-deficient tumor cell proliferation in neurofibromas, and coactivation of Runx1/3 in SCs and/or SCPs is important for neurofibroma initiation and growth." (PMID 31032403, 2019). "Interestingly, the polymorphism rs2151280 located in the lncRNA ANRIL (CDKN2B antisense RNA 1) was associated with the number of plexiform neurofibromas (PNFs) in NF1 patients, and 9p21.3 deletions, including the CDKN2A/B–ANRIL locus, are detected in PNFs." (PMID 31694342, 2019). "NF1 encodes the tumour suppressor protein neurofibromin, which negatively regulates the small GTPase Ras, with the constitutive activation of Ras signalling resulting from NF1 mutations being thought to underlie neurofibroma development." (PMID 29666462, 2018). "Our data thus suggest that tranilast may inhibit the growth of NF1-associated neurofibromas via suppression of EMT signalling and angiogenesis." (PMID 29666462, 2018). "In the context of neurofibroma, one can envision that the high number and proliferative status of Schwann cells triggered by nerve injury and loss of axonal contact would significantly increase the likelihood of biallelic NF1 inactivation." (PMID 29987131, 2018). "Thus far, other important NF1-associated tumors including plexiform neurofibromas, malignant peripheral nerve sheath tumors, and gastrointestinal stromal tumors have not been observed in our model." (PMID 30302402, 2018). "Neurofibromas are benign peripheral nerve tumors driven by NF1 loss in Schwann cells (SCs)." (PMID 28256556, 2017).